STAT6 (signal transducer and activator of transcription 6)
Diseases named in the same sentence as STAT6 in open-access papers (continued):
Sharing a sentence is not in itself a finding about the gene and the disease.
breast carcinoma (continued). "In contrast, in breast cancer, this miRNA is upregulated and promotes tumor cell proliferation through STAT6 regulation." (PMID 38146340, 2023). "SiRNA STAT6 sequences have been demonstrated to be able to inhibit the proliferation and induce apoptosis of colorectal HT-29 cancer cells and ZR-75-1 breast cancer cells, halving the number of cancer cells in a short period of time." (PMID 35327350, 2022). "For example, STAT6 activation promotes the malignant behavior of colon cancer, prostate cancer, breast cancer and mediastinal large B-cell lymphoma cells." (PMID 35269804, 2022). "Suppression of STAT6 phosphorylation by knockdown of lncRNA small nucleolar RNA host gene 1 (SNHG1) inhibited M2 macrophage polarization in breast cancer." (PMID 36153596, 2022). "Lastly, Yan and colleagues found that STAT6 is a direct target of miR-1207-5p in breast cancer, and the downregulation of STAT6 by miR-1207-5p is critical for the inhibition of clonogenicity of these cells." (PMID 33916548, 2021). "Collectively, our data demonstrated that p-STAT6 interacted with HDAC1 to repress PPP3CB gene transcription in Herceptin-resistant breast cancer cells." (PMID 33976188, 2021). "In HER2+ breast cancers, STAT6 is lost in 15 (7.6%) out of 197 patients, indicated that it is enriched in this subtype of breast cancer." (PMID 32525891, 2020). "Based on the samples analyzed by The Cancer Genome Atlas, we observed that STAT6 is lost in 45 (4.1%) patients out of total of 1093 patients across all breast cancer subtypes." (PMID 32525891, 2020). "STAT6 expression is lost in approximately 3% of breast cancers, but little work has been done in the context of trastuzumab resistance in breast cancer." (PMID 32525891, 2020). "The functions of STAT1, STAT3, STAT5, and STAT6 in breast cancer formation, progression, prognosis and prediction have been documented." (PMID 32754201, 2020). "Depletion studies in the mammary carcinoma system performed in vivo demonstrated that CD8+ T cells are essential for tumor rejection by STAT6−/− mice." (PMID 31798581, 2019). "The transcription factor STAT6 is strongly expressed in various tumours and is most highly expressed in human malignant lymphomas and pancreatic, colorectal, prostate and breast cancers." (PMID 31075146, 2019). "The STAT6 siRNA sequences therefore represent a potential treatment for STAT6high colorectal and breast cancers and a wide variety of other STAT6-expressing cancers." (PMID 31075146, 2019). "These experiments will be repeated in other STAT6high cancers in vitro, and animal studies in immunocompromised mice have been planned using xenografts of STAT6-expressing human colorectal and breast cancer cells." (PMID 31075146, 2019). "In humans, high levels of STAT6 have been detected in different cancer types, including glioblastoma, lymphoma, colorectal, prostate, pancreatic, and breast cancer." (PMID 31075146, 2019). "STAT6-defective mice have shown immunity to mammary carcinoma and also spontaneous rejection of implanted tumours." (PMID 31075146, 2019). "Although ODZ10117 inhibited the tyrosine phosphorylation of STAT3, it did not significantly affect other STAT family proteins, including STAT1, STAT5, and STAT6, in breast cancer cells and Hodgkin’s lymphoma cells." (PMID 31684051, 2019). "In mammary cancer, STAT6 knockout (KO) mice are 10 times more resistant to lung cancer metastasis than wild-type (WT) mice." (PMID 31798581, 2019). "Our results indicate that high mRNA expression of STAT6 is significantly associated with OS and RFS in breast cancer patients." (PMID 29326301, 2018). "STAT6 was found to be a novel target of PVT1-derived miR-1207-5p, and miR-1207-5p promoted breast cancer cell growth by targeting STAT6, which in turn control CDKN1A and CDKN1B, confirming the tumor suppressing role of STAT6 in breast cancer." (PMID 28422733, 2017).
breast carcinoma (continued). "STAT6 is induced by and required for IL-4-mediated growth inhibition and induction of apoptosis in human breast cancer cells, confirming its anti-tumor function in BC." (PMID 28422733, 2017). "This evidence is further supported by the Kaplan-Meier survival plotting analysis which indicated that high levels of STAT6 and TP63 expression were associated with longer DMFS of patients with breast cancer." (PMID 26208975, 2015). "Taken together, these data identify Stat6 as a coactivator of PR mediating the growth-inhibitory and differentiation effects of progesterone on breast cancer cells." (PMID 24401087, 2014). "Collectively, these data indicate a specific role for Stat6 as a coactivator of PR in the regulation of the progesterone-induced G1-phase cell cycle arrest of breast cancer cells." (PMID 24401087, 2014). "This therefore indicates that Stat6 specifically mediates the inhibition of breast cancer cell proliferation by PR." (PMID 24401087, 2014). "It is tempting to propose that p21 and p27 are involved in the Stat6-dependent effects on breast cancer cell differentiation." (PMID 24401087, 2014). "Additionally, inhibiting JMJD3 and STAT6 in macrophages increased cell apoptosis and decreased cell viability in breast cancer cells, while JMJD3 overexpression exhibited pro-tumor activity." (PMID 41955245, 2026). "Previous reports have shown that AS1517499, a STAT6 inhibitor, has the ability to hinder M2 polarization in vitro, which subsequently leads to a decrease in the tumor growth rates and metastasis in a 4T1 mammary carcinoma model." (PMID 37894541, 2023). "Further, pharmacological inhibition of the anti-inflammatory BDM and/or microglial phenotypes, via either Colony Stimulating Factor 1 Receptor (CSF-1R) or STAT6 pathways, significantly decreased tumour burden in two different syngeneic mouse models of breast cancer brain metastasis." (PMID 35359423, 2022). "STAT6 promotes the proliferation of colorectal cancer and breast cancer cells, but how STAT6 may exert certain functions on the biological properties of PC cells may need further exploration." (PMID 36335356, 2022). "The transcription factor KLF4 has been shown to be a key regulator of macrophage polarization in models of both prostate and breast cancer, and is activated through STAT6 signaling; this, in turn, is triggered through IL-4 signaling and participates in limiting the pro-inflammatory response." (PMID 35359423, 2022). "Thus, siRNA STAT6 sequences represent a potential treatment for colon and breast cancer with a high degree of STAT6, as well as a large number of other malignant tumors expressing STAT6." (PMID 35327350, 2022). "The results of these studies suggest that inhibition of STAT6 signaling by siRNA may provide a useful strategy for therapy of colorectal and breast cancers expressing high levels of STAT6." (PMID 33508033, 2021). "Meanwhile, MiR-1207-5p can target STAT6 to promote breast cancer growth, DNMT1 is a critical factor responsible for DNA methylation modification, VEGFA can trigger aberrant angiogenesis and induce immune evasion, and IGFBP5 is capable of regulating the insulin-like pathway." (PMID 34760687, 2021). "Finally, we also deleted STAT6 in the HER2-over-expressing breast cancer cell line BT474 in order to determine if our findings were also applicable to HER2-amplified breast cancer cells." (PMID 32525891, 2020). "However, some research groups suggest that STAT6 is necessary to inhibit growth and to mediate apoptosis via IL-4 in melanoma, colorectal, and breast cancer cells." (PMID 33076315, 2020). "In addition, blocking the IL-13 mediated phosphorylation of STAT6 can protect breast cancer cells from developing sensitivity to irradiation." (PMID 33569004, 2020).
breast carcinoma (continued). "In conclusion, these results demonstrate that STAT6 siRNA sequences are capable of inhibiting proliferation of and inducing apoptosis of HT-29 colorectal cancer cells and ZR-75-1 breast cancer cells, halving the number of cancer cells in a short period of time." (PMID 31075146, 2019). "In breast cancer, high expression of TP63 coupled with STAT6 has been shown to be associated with longer metastasis-free survival, indicating that TP63 could be involved in inhibiting the migration of breast cancer cells." (PMID 32010179, 2019). "STAT2, STAT4, STAT5a, STAT5b, and STAT6 had significantly favorable effect on RFS of breast cancer patients, but STAT1 had significant worse effect on RFS; STAT5b had significant favorable effect on PPS, while, STAT2 had significant worse effect on PPS for breast cancer patients." (PMID 29326301, 2018). "Using a combined gene set consisting of both groups of genes, we found that promoter regions with BRCA1 mutation-associated R-loops are enriched with binding sites for breast cancer-related transcription factors, such as GATA3 and FOXA1 in LP cells and SMAD2/4 and STAT6 in ML cells." (PMID 28649985, 2017). "Furthermore, IL13Ralpha2 silencing was associated with enhanced IL-13-mediated phosphorylation of signal transducer and activator of transcription 6 (STAT6) and impaired migratory ability of metastatic breast cancer cells." (PMID 26208975, 2015). "In fact, selective progesterone receptor modulators inducing Stat6 cofactor recruitment to PR could prevent breast cancer development when used in HRT, contraceptives, or treatment of uterine diseases." (PMID 24401087, 2014). "Stat6 deficiency did not affect the previously-reported rosiglitazone-induced inhibition of breast cancer cell growth." (PMID 24401087, 2014). "Thus, Stat6 is likely to mediate a positive feedback loop in the progesterone response that is crucial for the delayed and sustained action of progesterone on breast cancer cells." (PMID 24401087, 2014). "Therefore, the induction of a differentiated secretory phenotype of breast cancer cells by progesterone requires the expression of Stat6." (PMID 24401087, 2014). "It is noteworthy that Stat6 activities affect apoptosis and gene expression in breast cancer cells." (PMID 24401087, 2014). "Therefore, in the present study, we also investigated possible cross-talk between PR and Stat6 in the control of these cell cycle-regulating genes in the Stat6- and PR-expressing mammary carcinoma T47D cell line." (PMID 24401087, 2014). "Others have found that STAT6 loss is a negative prognostic marker in HER2-positive breast cancers." (PMID 32525891, 2020). "This study suggests that STAT6 may play a role in the pathophysiology of HER2+ human breast cancer." (PMID 32525891, 2020). "In view of the ability of Stat6 to function as a nuclear receptor coactivator, in this study we tested whether Stat6 interacts with PR and influences the progesterone-dependent regulation of mammary cancer cell growth." (PMID 24401087, 2014). "CircWWC3 can increase IL-4 expression and secretion in breast cancer cells, and IL-4 binding to this receptor can activate PI3K and STAT6, as well as enhance M2-like polarization of macrophages in TME, and M2 further promotes breast cancer cells." (PMID 38523627, 2024). "It has been reported that AS can inhibit tumor growth and early liver metastasis in a 4T1 mammary carcinoma mouse model by inhibiting TAM-induced pro-tumorigenic and pro-metastatic activities via STAT6." (PMID 37175092, 2023). "An example of this is the STAT6 inhibitor, AS1517499, which has been shown to inhibit M2 macrophage polarization, thereby reducing breast cancer growth and metastasis." (PMID 37173951, 2023). "Specifically, PYK2 ablation inhibits Notch1 signaling and consequently reduces CCL2 secretion by breast cancer cells, and concurrently reduces the levels of CCR2, CXCR4, IL‐4Rα, and Stat6 activation in macrophages." (PMID 35092356, 2022).
breast carcinoma (continued). "STAT6 interacted with SP1 and increased the expression of p21 and p27 in promoting breast cancer cell proliferation." (PMID 35600336, 2022). "For instance, PVT1 upregulates the expression of miR-1207-5p to repress the expression of signal transducer and activator of transcription 6 (STAT6) and cyclin inhibitors, thus enhancing cell proliferation and colony formation in breast cancer." (PMID 34527584, 2021). "Taken together, our results successfully demonstrated that the expression of the immune cell subtype-related proteins STAT6, FOXP3, CD8, CD68, and CD163 was different according to the molecular subtype of breast cancer." (PMID 32580398, 2020). "Overexpression of STAT6 mRNA were significantly related to favorable OS (HR =0.73 (0.59–0.91), P=0.043 and PFS (HR =0.62 (0.55–0.69), P<0.001) for all the breast cancer patients." (PMID 29326301, 2018). "Cancer cell growth-inhibitory effect of STAT6 was shown to be mediated by induction of the G1 cyclin-dependent kinase inhibitors p21Cip1/WAF1 and p27Kip1 in human breast cancer cells." (PMID 26993600, 2016). "To decipher the molecular basis for how targeting IL13Rα2 suppressed breast cancer metastasis, we examined the phosphorylation status of STAT proteins and found enhanced STAT6 phosphorylation as the major downstream signaling mediator." (PMID 26208975, 2015). "The characterization of Stat6 as a PR coregulator molecule involved in the antiproliferative and differentiation effects of progesterone in breast tissue could potentially explain the biological effects of different progestins on breast cancer and guide the future discovery of drugs." (PMID 24401087, 2014). "Recently, we identified a new function for Stat6 as a growth suppressor protein in CHO and mammary cancer cells (in submission)." (PMID 24401087, 2014). "Next, we determined whether DVL2 binds to the promoter regions of genes involved in antigen presentation (HLA-A, HLA-C) and T-cell maintenance (STAT1, STAT6, TGFB1) in HER2-positive breast cancer cells." (PMID 36809986, 2023). "It was previously shown that STAT6 sites could specifically bind STAT6 activated by IL4 in several cell lines, such as human breast cancer cells and normal human prostate epithelial cells (PrEC)." (PMID 36362361, 2022). "Notably, these TFs and other TFs like STAT6 and CCDN1 are directly involved in developing breast cancer and its metastasis." (PMID 35388653, 2022). "On comparing the number of immune cells expressing immune cell subtype-related proteins, we found that the expression of STAT6 (p = 0.005), FOXP3 (p = 0.001), CD8 (p = 0.012), CD68 (p = 0.011), and CD163 (p < 0.001) differed significantly according to the breast cancer molecular subtypes." (PMID 32580398, 2020). "In breast cancer cells, the depletion of STAT6 demonstrated that this protein participates in the negative regulation of CD8+ T cells, which are essential for tumor rejection." (PMID 32244885, 2020). "A similar link between IL4-induced apoptosis and Stat6 has previously been reported in breast cancer, but not in AML." (PMID 28819278, 2018). "Conversely, lacking STAT6 in mouse model enhances tumor immunity to both primary and metastatic mammary carcinomas." (PMID 27533463, 2016). "Consistently, previous study reports no PR binding in the Stat6 promoter in T-47D breast cancer cells." (PMID 24401087, 2014). "In breast cancer, up to 18% of breast tumors have decreased or absent STAT6 mRNA expression." (PMID 32525891, 2020). "Importantly, targeted depletion of IL13Rα2 resulted in dramatic suppression of lung metastasis formation in vivo that is likely to be attributed, at least in part, to STAT6-dependent induction of tumor protein 63 (TP63) expression and suppression of breast cancer cell migration." (PMID 26208975, 2015).
breast carcinoma (continued). "Finally, based on this evidence, we hypothesized that if a metastasis suppressing IL-13-STAT6-TP63 signaling axis is activated in the absence of IL13Rα2 then STAT6 and TP63 expression levels may coordinately predict survival of patients with breast cancer." (PMID 26208975, 2015).